GOLPH3 (golgi phosphoprotein 3)
Diseases named in the same sentence as GOLPH3 in open-access papers (continued):
Sharing a sentence is not in itself a finding about the gene and the disease.
bladder cancer (6 papers, 2015 to 2025). "We found that the GOLPH3 levels are associated with the T classification (NMI or MI) in older people (P = 0.047), which indicates that increased GOLPH3 expression is associated with the progression of bladder cancer in older patients." (PMID 26375441, 2015). "Knockdown of GOLPH3 decreased the proliferation, migration and invasion of bladder cancer cells and the tumor growth in xenograft mice, which may be associated with GOLPH3 modulation of AKT/mTOR signaling." (PMID 26375441, 2015). "Moreover, univariate and multivariate analyses further suggested that GOLPH3 is an independent predictor of the survival of patients treated by cystectomy and is associated with bladder cancer progression." (PMID 26375441, 2015). "The role of GOLPH3 in bladder cancer cell migration and invasion may associated with MMP9 expression, and its underlying mechanism needs to be explored further." (PMID 26375441, 2015). "Statistical analysis indicated that the GOLPH3 expression was strongly associated with the Ki67 expression level (P = 0.002), suggesting that GOLPH3 overexpression may contribute to the proliferation of human bladder cancer." (PMID 26375441, 2015). "Here, we show that GOLPH3 is frequently overexpressed in bladder cancer treated by cystectomy, and this highexpression is significantly associated with worse prognosis." (PMID 26375441, 2015). "In conclusion, this study suggests that GOLPH3 is overexpressed in most bladder cancers treated by cystectomy and plays an important role in human bladder cancer progression by modulating AKT/mTOR signaling." (PMID 26375441, 2015). "In this study, we sought to analyze the GOLPH3 expression in bladder cancer samples and cells, and explore its clinical significance and biological role." (PMID 26375441, 2015). "Overexpression of GOLPH3 had significant correlation with poorer survival for bladder cancer patients treated by cystectomy." (PMID 26375441, 2015). "It is surprising that intratumoral injection with GOLPH3 siRNA#1, which induced the inhibition of GOLPH3 expression, significantly inhibited the growth of bladder cancer cells in nude mice." (PMID 26375441, 2015). "GOLPH3 silencing in bladder cancer cells decrease the cell proliferation, migration and invasion likely by inhibiting AKT/mTOR signaling." (PMID 26375441, 2015). "Here, we first found that GOLPH3 was significantly increased in a large cohort of human bladder cancer tissues." (PMID 26375441, 2015). "We found that GOLPH3 knockdown strikingly inhibited the proliferation and growth of bladder cancer cells in vitro and in vivo." (PMID 26375441, 2015). "Western blot and real-time PCR analyses showed that the GOLPH3 expression level in most human bladder cancer tissues was higher than that in paired ANT and NB." (PMID 26375441, 2015). "Together, our data highlight an important role for GOLPH3 in controlling bladder cancer progression and its promise as a therapeutic target and novel prognostic indicator for poor survival in bladder cancer." (PMID 26375441, 2015). "Strikingly, we found that the areas in the bladder cancer specimens displaying high levels of GOLPH3 staining also had strong Ki67 staining signals, and areas with low GOLPH3 expression had weakly detectable Ki67 expression." (PMID 26375441, 2015). "In this study, we found that GOLPH3 protein and mRNA expression are significantly increased in T24 and J82 bladder cancer cells compared with seven other bladder cancer cell lines and the immortalized normal human uroepithelium cell line SV-HUC-1." (PMID 26375441, 2015). "The key findings of this study are that GOLPH3 is overexpressed in most bladder cancer tissues and cell lines, which predicts poor survival for bladder cancer patients treated by cystectomy." (PMID 26375441, 2015). "Similarly, in bladder cancer, miR-1 mediates tumor suppression by directly targeting Golgi phosphoprotein 3 (GOLPH3), inhibiting FOXO1 and AKT phosphorylation." (PMID 41373864, 2025).
bladder cancer (continued). "Furthermore, in bladder cancer, downregulation of miR-34a resulted in GOLPH3 overexpression, and ectopic expression of miR-34a decreased the stem cell properties of chemo-resistant urothelial bladder cancer cells." (PMID 34345203, 2021). "Moreover, an in vivo metastasis assay and studies of the underlying mechanism of the observed migration and invasion should be performed to further validate the role of GOLPH3 in metastasis in human bladder cancer." (PMID 26375441, 2015). "This study provides new insight and strong evidence that GOLPH3 is functionally important in the progression of bladder cancer, it may serve as novel prognostic indicator for poor survival and is a target for bladder cancer therapy." (PMID 26375441, 2015). "Full understanding of the precise role of GOLPH3 in human bladder cancer may provide an opportunity for developing a novel therapeutic strategy by suppressing the expression of GOLPH3." (PMID 26375441, 2015). "Furthermore, the MMP9 expression level was drastically reduced in GOLPH3-silenced cells compared with control cells accompanied by significantly increased levels of MMP9 in bladder cancer tissues compared with ANT." (PMID 26375441, 2015). "To further examine the functional role of GOLPH3 in bladder cancer cells, we specifically knocked down its expression using siRNA in T24 and J82 cells, which express the highest levels of endogenous GOLPH3 of 7 tested bladder cancer cell lines." (PMID 26375441, 2015). "Furthermore, comparative analysis revealed that the GOLPH3 protein and mRNA expression were significantly increased in all of the 7 tested bladder cancer cell lines compared with the normal human uroepithelium cell SV-HUC-1." (PMID 26375441, 2015). "We found that GOLPH3 was significantly increased in bladder cancer tissues and cells." (PMID 26375441, 2015). "Consequently, GOLPH3 appeared to be a critical factor for proliferation and tumorigenicity; therefore, it should be a good therapeutic target for halting the proliferation of bladder cancer." (PMID 26375441, 2015). "Furthermore, we strikingly found that the expression of GOLPH3 was strongly associated with the Ki67 expression level (P = 0.002), suggesting that GOLPH3 overexpression may contribute to the proliferation and tumorigenicity of bladder cancer." (PMID 26375441, 2015). "In addition, our study demonstrates that knockdown of endogenous GOLPH3 in bladder cancer cells greatly reduces the cell migration and invasion capacity in vitro, suggesting that GOLPH3 plays an important role in bladder cancer invasiveness." (PMID 26375441, 2015). "However, the clinical significance and biological role of GOLPH3 in bladder cancer remains unclear." (PMID 26375441, 2015). "Thus, GOLPH3 is likely to play important roles in bladder cancer progression via modulating AKT/mTOR signaling, and it is a novel prognostic biomarker and promising therapeutic target for bladder cancer." (PMID 26375441, 2015). "To investigate whether GOLPH3 silencing had inhibitory effects on tumor growth in vivo, we first established stable T24 bladder cancer cell lines expressing GOLPH3 or negative control short hairpin RNAs." (PMID 26375441, 2015). "However, the GOLPH3 levels were not significantly correlated with clinicopathological characteristics except for the age of the patients with bladder cancer in this cohort, possibly due to the limited number of patients." (PMID 26375441, 2015).
lymph node metastasis (5 papers, 2012 to 2022). "Seven studies 11, 16, 24, 25, 27-29 revealed the correlation between the expression level of GOLPH3 and different status of lymph node metastasis in patients with NSCLC, including 354 cases with lymphatic metastasis and 531 cases without lymphatic metastasis." (PMID 31737112, 2019). "We further examined the prognostic value of GOLPH3 expression in different subgroups of ESCC patients stratified according to the clinical stage, T classification, and lymph node metastasis." (PMID 23056210, 2012). "Similar results were found between patients in the high and low GOLPH3 expression groups, with and without lymph node metastasis (both P < 0.001), with and without liver metastases (P < 0.001)." (PMID 25104140, 2014). "The overall survival of patients with high and low GOLPH3 levels was compared within subgroups of clinical-stage, T classification, lymph node metastasis, and distant metastasis, which revealed a negative correlation between patient prognosis and GOLPH3 levels." (PMID 35190555, 2022). "Similarly, the overall survival was significantly shorter in patients with high GOLPH3 expression in both the T1+T2 subgroup (n = 54, P<0.0001) and the T3+T4 subgroup (n = 101, P<0.0001), or in lymph node metastasis negative (n = 78, P = 0.003) and positive patients (n = 77, P<0.0001)." (PMID 23056210, 2012).
renal cell carcinoma (5 papers, 2014 to 2020). "In a study of human renal cell carcinoma (RCC), the proto-oncogene Golgi phosphoprotein 3 (GOLPH3) was able to activate simultaneously the FAK/Raf/MEK pathway and Wnt/β-catenin promoting RCC cell proliferation and malignancy." (PMID 33266025, 2020).
benign prostatic hyperplasia (4 papers, 2012 to 2023). A non-cancerous nodular enlargement of the prostate gland. "Immunohistochemical analysis of GOLPH3 and YB-1 in different lesions of the prostate that included 20 benign prostatic hyperplasia (BPH), 20 prostatic intraepithelial neoplasia (PIN) and 67 PC cases was done." (PMID 28983350, 2015).
esophageal cancer (4 papers, 2012 to 2024). A primary or metastatic malignant neoplasm involving the esophagus. "Whether the expression of Golgi phosphoprotein 3 (GOLPH3) correlates with esophageal cancer tumorigenesis is currently unclear." (PMID 23056210, 2012). "GOLPH3's relation with esophageal cancer, however, remains unclear." (PMID 23056210, 2012).
pancreatic cancer (4 papers, 2014 to 2024). "Abnormal expression of GOLPH3 has been detected in various gastrointestinal cancers including gastric, colorectal and pancreatic cancers." (PMID 37508488, 2023). "The exact mechanism following DNA damage through Golgi response to regulate cell survival and function of GOLPH3 in pancreatic cancer as well, will be explored in our further studies." (PMID 25104140, 2014). "When GOLPH3 and STIP1 are knocked down, they can not only inhibit the proliferation of pancreatic cancer cells, but also inhibit the expression of cyclin D1 in cancer cell." (PMID 38594465, 2024). "This study also showed that the overexpression of GOLPH3 was positively correlated with the expression of STIP1 in pancreatic cancer tissue, but the knockout of GOLPH3 did not affect the level of STIP1." (PMID 38594465, 2024).
brain tumor (3 papers, 2020 to 2021). "By contrast, compared to monotherapies, co-delivery of siRNA targeting GOLPH3 and gefitinib in brain tumours reduces cancer progression and improves mice survival." (PMID 34831480, 2021).
colon adenocarcinoma (3 papers, 2014 to 2025). "In the present study, PSB suppressed cell viability and accelerated the apoptosis of 5-FU-resistant colon adenocarcinoma cells by regulating the LINC00612/miR-590-3p/GOLPH3 axis (Graphical abstract)." (PMID 38806777, 2024). "PSB attenuates 5-FU chemoresistance in colon adenocarcinoma by regulating the LINC00612/miRNA-590-3p/GOLPH3 axis." (PMID 38806777, 2024). "The role of the LINC00612/miR-590-3p/Golgi phosphoprotein 3 (GOLPH3) axis was determined in 5-FU-resistance colon adenocarcinoma cells." (PMID 38806777, 2024). "Moreover, GOLPH3 knockdown reversed the effects of LINC00612 on 5-FU-resistance in colon adenocarcinoma cells." (PMID 38806777, 2024). "In colon adenocarcinoma, it has been revealed that GOLPH3 is amplified at the 5p13 region." (PMID 24444035, 2014). "Mechanistically, LINC00612 specifically bound to miR-590-3p, which promoted 5-FU resistance in colon adenocarcinoma cells and attenuated the inhibitory effect of LINC00612 on GOLPH3 expression." (PMID 38806777, 2024). "In the chemoresistance of colon adenocarcinoma (COAD), USP6 directly controlled the GOLPH3 protein’s deubiquitination and improved its stability." (PMID 40348771, 2025).
neuroblastoma (3 papers, 2019 to 2023). Neuroblastoma (NB) is the most common solid, extracranial childhood tumor. "A recent study showed that GOLPH3 is upregulated in neuroblastoma N2A cells upon oxygen-glucose deprivation and reoxygenation to promote stress-related autophagy, ROS production, and apoptotic cell death." (PMID 37479687, 2023). "A more recent study from Ognibene and collaborators analyzed the effects of curcumin on DNA damage in two human neuroblastoma cell lines, reporting an increase of GOLPH3 expression accompanied by Golgi fragmentation and increased expression of TPX2 oncoprotein." (PMID 32023813, 2020). "Our findings suggest that GOLPH3 expression levels may represent a clinical marker of neuroblastoma patients’ responsiveness to DNA damaging therapies—and of possible resistance to them." (PMID 31557970, 2019).
rectal cancer (3 papers, 2016 to 2018). A primary or metastatic malignant neoplasm that affects the rectum. "Then, the associations of GOLPH3 with pathological characteristics and prognosis of rectal cancer were assessed." (PMID 27634904, 2016). "This is the first study to assess the associations of the new oncogene-GOLPH3 and nCRT in rectal cancer." (PMID 27634904, 2016). "The aim of this study was to assess GOLPH3 expression in rectal cancer, and determine its associations with clinical pathological characteristics and prognosis, evaluating its value as a potential independent predictive indicator for nCRT sensitivity and prognosis." (PMID 27634904, 2016). "GOLPH3 was highly expressed in rectal cancer cell cytoplasm, with 77 (52.03%) cases showing high expression." (PMID 27634904, 2016). "Multiple-factor analysis indicated that pN and pT were important prognosis factors for rectal cancer, as well as GOLPH3 expression." (PMID 27634904, 2016). "In this study, mTOR was also highly expressed in rectal cancer tissues, and 81 cases with high expression (81/148, 54.73%) were obtained, which was consistent with high GOLPH3 expression." (PMID 27634904, 2016). "Whether the mTOR pathway is targeted by GOLPH3, with its inhibition reversing resistance to radiotherapy in rectal cancer needs to be addressed in future studies." (PMID 27634904, 2016). "Two reports assessing GOLPH3 in rectal cancer have been published." (PMID 27634904, 2016). "In conclusion, this study demonstrated that GOLPH3 was highly expressed in rectal cancer, and could predict sensitivity to nCRT in LARC; effect was better in patients with low expression." (PMID 27634904, 2016). "Multi-factor analysis showed that GOLPH3 was an independent predictive factor for TRG (OR = 3.952; CI 1.655–10.327, P = 0.026) and tumor down-staging (OR = 2.951; CI 1.523–11.324, P = 0.021), suggesting GOLPH3 could reliably and independently predict sensitivity to nCRT in rectal cancer." (PMID 27634904, 2016). "Finally, GOLPH3 was shown to be an independent prognosis factor for rectal cancer." (PMID 27634904, 2016). "For example, high GOLPH3 overexpression correlates with a worse DFS in small cell lung cancer, prostate cancer, ovarian epithelial cancer, hepatoma carcinoma, and rectal carcinoma." (PMID 29285241, 2017). "However, there is no report available to assess the relationship between GOLPH3 and efficacy of nCRT for rectal cancer." (PMID 27634904, 2016). "Indeed, GOLPH3 was shown to be an independent prognosis indicator for 5 year-DFS (HR = 2.624; 95% CI 1.235–6.541, P = 0.009) and OS (HR = 2.354; 95% CI 1.237–6.152, P = 0.039) in rectal cancer." (PMID 27634904, 2016).
rhabdomyosarcoma (3 papers, 2012 to 2018). A rare aggressive malignant mesenchymal neoplasm arising from skeletal muscle. "Human rhabdomyosarcoma cell lines and biopsy specimens exhibited an increased expression of both GOLPH3 and GOLPH3-like (GOLPH3L) mRNA and protein." (PMID 23056210, 2012). "Knockdown of the GOLPH3 prevented the proliferation in human rhabdomyosarcoma cell." (PMID 29534690, 2018). "In addition, GOLPH3 and GOLPH3L knockdown by small interfering RNA prevented the proliferation of human rhabdomyosarcoma cell lines." (PMID 23056210, 2012).
tongue squamous cell carcinoma (3 papers, 2012 to 2023). A squamous cell carcinoma that arises from the tongue. "According to our previous study, GOLPH3 is markedly up‐expressed in tongue squamous cell carcinoma (TSCC), which is also associated with poor survival." (PMID 32307911, 2020). "Interaction between SRY-box transcription factor 8 (SOX8) and TFAP2A increases Golgi phosphoprotein 3 (GOLPH3) promoter activity and tumor growth of tongue squamous cell carcinoma." (PMID 37291585, 2023).
Cerebral ischemia (2 papers, 2021 to 2025). Restriction of arterial blood supply to the brain associated with insufficient oxygenation to support the metabolic requirements of the tissue. "The mechanism of Golgi apparatus (GA) stress responses mediated by GOLPH3 has been widely studied in ischemic stroke, and the neuroprotection effect of olfactory mucosa mesenchymal stem cells (OM-MSCs) against cerebral ischemia/reperfusion injury (IRI) has been preliminarily presented." (PMID 34815829, 2021).
ischemic stroke (2 papers, 2021 to 2025). A stroke disorder caused by obstruction of blood flow to the brain, due to thrombotic (local blood clot formation) or embolic (due to a blood clot or other material traveling from another site) event. "In summary, the present data demonstrated that OM-MSCs downregulated GOLPH3 expression, upregulated SPCA1 expression, inhibited ROS production, and alleviated intracellular Ca2+ overload in ischemic stroke models via secretion of PEDF." (PMID 34815829, 2021). "Our results showed that the level of GOLPH3 protein, reactive oxygen species (ROS), and Ca2+ was upregulated, SPCA1 level was downregulated, and GA fragmentation was increased in ischemic stroke models, and OM-MSC treatment clearly ameliorated these GA stress responses in vitro and in vivo." (PMID 34815829, 2021).
Lymphatic Metastasis (2 papers, 2017 to 2019). Transfer of a neoplasm from its primary site to lymph nodes or to distant parts of the body by way of the lymphatic system. "Similar results were observed in our study in patients with high GOLPH3 expression with advanced lymphatic metastasis." (PMID 29285241, 2017). "For patients without lymphatic metastasis (N0), high GOLPH3 expression indicated poor DFS (p=0.0004) and OS (p=0.0166)." (PMID 29285241, 2017).
oral squamous cell carcinoma (2 papers, 2022 to 2024). "The function of circular GOLPH3 RNA (circGOLPH3) in oral squamous cell carcinoma (OSCC) is unclear." (PMID 35481460, 2022).
pancreatic ductal adenocarcinoma (2 papers, 2014 to 2020). An infiltrating adenocarcinoma that arises from the epithelial cells of the pancreas. "Overexpression of Golgi phosphoprotein 3 (GOLPH3) predicts poor prognosis and is a potential therapeutic target in pancreatic ductal adenocarcinoma (PDAC)." (PMID 33134174, 2020). "Golgi phosphoprotein 3 (GOLPH3) has been identified as an oncoprotein in various human cancers; however, its role in pancreatic ductal adenocarcinoma (PDAC) is unknown." (PMID 25104140, 2014).
acral lentiginous melanoma (1 paper, 2016). A form of melanoma occurring most often on the plantar, palmar, subungual, and periungual skin. "Overexpression of GOLPH3 was more frequently observed in nodular and acral-lentiginous melanomas." (PMID 27706081, 2016).
asthma (1 paper, 2013). "Of the top two regions, KCNIP4 and PDZD2/GOLPH3/MTMR12/ZFR, only KCNIP4 had gene-level replication in the SHARP AHR GWAS at a nominally significant level in the same regions as the asthma GWAS studies." (PMID 23457522, 2013).